CTLA4 (cytotoxic T-lymphocyte associated protein 4)
Diseases named in the same sentence as CTLA4 in open-access papers (continued):
Sharing a sentence is not in itself a finding about the gene and the disease.
cancer (continued). "The CTLA4 gene modulates immune response by serving as checkpoints for T-cell activation, essentially decreasing the T cells’ ability to attack cancer cells." (PMID 34068918, 2021). "In humans, the correlation between high levels of CTLA-4 expression and poor outcome is well established in several types of cancer." (PMID 33401460, 2021). "Blocking the expression of PD-1 and CTLA-4 improved the outcomes of patients in different cancers, but immune-related adverse events were observed." (PMID 33643388, 2021). "Targeting the inhibitory CTLA4 or PD-1/PD-L1 with monoclonal antibodies has shown striking antitumor activity in patients with cancers, and a number of these objective responses seemed to be durable." (PMID 33416945, 2021). "Undoubtedly, the discovery of immune checkpoints such as CTLA-4 and PD-1 played a key role in the development of cancer immunotherapy." (PMID 34305910, 2021). "Extensive interest in cancer immunotherapy is reported according to the clinical importance of CTLA-4 and (PD-1/PD-L1) [programmed death (PD) and programmed death-ligand (PD-L1)] in immune checkpoint therapies." (PMID 34778071, 2021). "Immunotherapies represented by targeting PD-1/ PD-L1 and CTLA-4/B7 pathways have shown remarkable clinical efficacies against various cancer types." (PMID 34088360, 2021). "All patients had a cancer diagnosis and were treated with ICIs (anti-PD-1, anti-PD-L1 and anti-CTLA-4-inhibitor) mono or combination therapy." (PMID 34365980, 2021). "Immune checkpoint inhibitors against PD-1, PD-L1 and CTLA-4 have altered the treatment paradigm for various types of cancers in the past decade." (PMID 33909103, 2021). "Although these therapies are effective for many cancer patients, complete response rate ranges from around 20% for anti-CTLA-4 antibody therapy to 30% for anti-PD/anti-PD-L1 therapy in the case of melanoma." (PMID 33547395, 2021). "Many cancer vaccines currently in clinical trials are combined with a checkpoint inhibitor such as CTLA-4, PD-1 or PD-L1 inhibitors, which are offered as standard treatment for an increasing number of cancers." (PMID 33859638, 2021). "We found that administration of anti-CTLA-4 improved the anti-cancer activity of T cells with reduced proliferation and viability of MDA-MB-231." (PMID 34440813, 2021). "Blockade of PD-1/PD-L1 and CTLA-4 has achieved significant therapeutic success in a variety of cancers." (PMID 34220965, 2021). "Immunosurveillance influences the prognosis of cancer patients, and tumors evade immune responses by taking advantage of immune checkpoints, such as PD-1, PD-L1, and CTLA-4." (PMID 34239690, 2021). "Treatment with immune checkpoint inhibitors (ICIs) targeting CTLA-4 and the PD-1/PD-L1 axis is effective against many cancer types." (PMID 34461854, 2021). "Both pathways were identified (CTLA4 Signaling in Cytotoxic T Lymphocytes and PD-1, PD-L1 cancer immunotherapy pathway), as additional validation for this screening." (PMID 34070461, 2021). "CTLA-4, PD-1, and PD-L1 antibody immunotherapy have demonstrated significant effectiveness for the treatment of some cancers." (PMID 34454491, 2021). "One of the mechanisms of cancer immune escape is via the activation of immunosuppressive signaling pathways, among which, the PD-1/PD-L1 pathway and CTLA-4 pathway have been extensively studied." (PMID 34659197, 2021). "Antibodies that block the PD-1 and PD-L1 axis or CTLA-4 have been developed and are able to produce durable clinical responses and prolong overall survival in cancer patients." (PMID 33514004, 2021). "This study aimed to use clinical specimens and bioinformatic tools to assess the CTLA-4 expression in cancer and adjacent samples." (PMID 34067631, 2021). "To date, immune checkpoint inhibitors targeting PD1/PDL1 and CTLA4 have transformed the care of patients with advanced-stage cancers, most effectively for melanoma, renal, head and neck, bladder, and Hodgkin lymphoma." (PMID 34068491, 2021).
cancer (continued). "CTLA-4 is a transmembrane receptor of T cells, which binds to B7 segment of the T cells in order to down-regulate their immune response against cancer cells." (PMID 34357119, 2021). "In clinical practice, PD-1/-L1 and CTLA-4 inhibitor are being combined with other anti-cancer drugs including chemotherapy, targeted therapy, radiotherapy and other immunotherapies." (PMID 34447305, 2021). "Immune checkpoint blocking therapy (ICB), which targets programmed cell death ligand 1 (PDL1) and cytotoxic T lymphocyte antigen 4 (CTLA4) pathways, has become a treatment strategy for various types of cancer." (PMID 34795697, 2021). "This was based on the rationale that cancer vaccines induced antigen-specific T-cells to upregulate CTLA4, a negative regulatory molecule, and that CTLA4 blockade can prevent this and enhance T-cell-mediated immune responses to the vaccine." (PMID 34063238, 2021). "Currently, immunotherapy, receiving extensive attention all around the world, has been demonstrated as a groundbreaking remedy for cancer patients by blocking CTLA-4 or PD-1 pathways." (PMID 34108990, 2021). "The most well-known coinhibitory receptors are perhaps CTLA-4 and PD-1 due to the application of checkpoint blockade in cancer immunotherapy." (PMID 33717075, 2021). "Targeting key immune checkpoints, such as programmed death-1 (PD-1) or its ligand (PD-L1) and cytotoxic T-lymphocyte antigen-4 (CTLA-4), with antibodies is now a recognized treatment option for several cancers." (PMID 33672515, 2021). "Immunosuppression is mediated by cancer cells expressing programmed death-ligand 1 (PD-L1) and CD80 that bind PD-1 and cytotoxic T-lymphocyte-associated protein 4 (CTLA4) on cytotoxic T cells to suppress T cell activation." (PMID 33406733, 2021). "Considering the higher expression of PD-L1 in NPC, the use of PD-1 inhibitors, such as nivolumab, or a dual CTLA-4/PD-1 blockade appear to be an effective strategy for the treatment of this cancer form." (PMID 35387050, 2021). "Since FDA approval of the first ICI, ipilimumab, in 2011, a growing portfolio of monoclonal antibodies targeting the CTLA-4 and PD-1/PD-L1 pathways has emerged, which purport therapeutic advantage over a broad spectrum of cancers." (PMID 34675810, 2021). "In accordance with the results observed in the proliferation assay, inhibition of CTLA-4 on the surface of PBMC allowed for the significant arrest of MDA-MB-231 cancer cells in the G1/S-phase of the cell cycle." (PMID 34440813, 2021). "Immune checkpoint blockade therapies, such as PD-1, PD-L1 and CTLA-4 blockade have revolutionized the treatment of cancer." (PMID 33391977, 2021). "Immunotherapies have changed the methods of cancer treatment subversively, such as the application of checkpoint inhibitors targeting PD-1 and CTLA-4." (PMID 33648605, 2021). "The results showed that SMARCC1 expression was obviously associated with the expression of immune checkpoints on immune cells and cancer cells, including PD-1, PD-L1, PD-L2, and CTLA-4." (PMID 34937564, 2021). "Our data suggest a novel therapeutic indicator for evaluating the sensitivity of anti‐PD‐1 or anti‐CTLA‐4 treatments in patients with cancer, and further studies should be applied to validate these results in clinical trials." (PMID 33934451, 2021). "The co-inhibitory receptor, CTLA4, is also highly expressed on Tregs and plays critical roles in cancer immunity." (PMID 34248973, 2021). "A blockade of landmark immune checkpoints expressed on immune and cancer cells, namely the cytotoxic T-lymphocyte antigen 4 (CTLA-4), programmed cell death (PD) 1 (PD-1), and the ligand of the latter (PD-L1), harnesses the immune system to attack cancer cells." (PMID 34771441, 2021). "The novel CTLA4 inhibitors developed in this study have potential to treat canine cancer patients and to integrate them in immuno-oncology research." (PMID 34675296, 2021).
cancer (continued). "In recent years, various different inhibitory immuno-receptors, also known as immune checkpoints, have been identified and analyzed for their role in cancer, including but not limited to PD-1, CTLA-4, LAG3, TIM3, TIGIT, and BTLA." (PMID 33746972, 2021). "Many studies have shown that CTLA-4 is highly expressed in cancer cells and can be used for early diagnosis, treatment monitoring, and prognosis prediction of cancer." (PMID 34553071, 2021). "Despite the promising impact of cancer immunotherapy targeting CTLA4 (e.g. ipilimumab) and PD1/PDL1 (e.g. pembrolizumab), with in-depth research, the side effects and resistance of these drugs have gradually emerged." (PMID 34267742, 2021). "Cancer immunotherapy, which is mainly based on immune checkpoint inhibitors, such as those for PD-1, PD-L1, and CTLA4, is an effective treatment method." (PMID 34065315, 2021). "Currently, the checkpoints of programmed cell death protein 1(PD-1)/programmed cell death ligand 1(PDL1) and cytotoxic T lymphocyte antigen-4 (CTLA4) are widely exploited for cancer immunotherapy." (PMID 35008249, 2021). "One of the most promising combination immunotherapies is the use of cancer vaccines with checkpoint inhibitors (eg, anti-PD-1/PD-L1 and anti-CTLA-4)." (PMID 33860227, 2021). "The success of ICIs, such as anti-CTLA-4 and anti-PD-1/PD-L1, in combination with chemotherapy, immunotherapy, and targeted agents, has changed the paradigm of cancer treatment." (PMID 34025438, 2021). "Intervening PD1/PDL1 and CTLA4 pathways emerged as cancer immunotherapy modalities with efficacy and are being actively pursued." (PMID 34070461, 2021). "Methylation has been shown to regulate the expression of PD-1, PD-L1, and CTLA-4 in various cancers." (PMID 34067904, 2021). "Our study surmises that PD-1/PD-L1 inhibitors as well as combination therapy with CTLA-4 and PD-1 inhibitors show encouraging response rates in mCRC patients, albeit exclusively in patients with cancer that are of MSI-H status." (PMID 34503155, 2021). "Drugs that target ICPs, including but not limited to anti-CTLA-4 and anti-PD-1/PD-L1, significantly improve the prognosis of advanced cancer patients." (PMID 33608497, 2021). "Immune checkpoint inhibitors (ICIs), such as programmed death-1 (PD-1)/programmed death ligand-1 (PD-L1) and cytotoxic T-lymphocyte-associated protein 4 (CTLA4) antibodies, are widely administered to patients with several types of cancers." (PMID 34833490, 2021). "Some other mAbs such as Tremelimumab (anti-CTLA-4, IgG2) are progressing in preclinical and clinical trials to use single or combine with other agents for different types of cancers." (PMID 35083014, 2021). "LAG-3 plays a regulatory role in immunity and emerged some time ago as an inhibitory immune checkpoint molecule comparable to PD-1 and CTLA-4 and a potential target for enhancing anti-cancer immune responses." (PMID 34067904, 2021). "Inhibitory immune checkpoint blockade by anti-CTLA-4, anti-PD-1, or anti-PD-L1 antibodies has provided substantial benefits to advanced cancer patients." (PMID 34881181, 2021). "Although blocking the immune checkpoints with anti-PD-1, anti-PD-L1 and anti-CTLA4 has shown promising results and is an effective strategy for many other types of cancers, their ability to bolster the immune response is limited in the case of GBM." (PMID 33790740, 2021). "Patients with advanced NSCLC and other cancers demonstrate better prognosis upon treatment with anti-PD-1 and anti-CTLA-4 therapies." (PMID 33795529, 2021). "As an important strategy of cancer immunotherapy, CTLA4 blockade results in broad enhancement of immune responses that are dependent on helper T cells." (PMID 34094935, 2021). "Immune response checkpoint regulators including CTLA-4 and PD-1 have been shown to play a critical role in cancer development through interactions with B7 proteins, particularly CD80 and CD86." (PMID 34440813, 2021).
cancer (continued). "Immune checkpoint blockade (ICB) targeting T cell inhibitory receptors: cytotoxic T lymphocyte associated protein-4 (CTLA-4) and programmed cell death protein-1/ligand-1 (PD-1/PD-L1) have revolutionized cancer treatment." (PMID 33987104, 2021). "ICIs targeting PD-1/PD-L1 and CTLA-4 has proved to be a breakthrough in cancer treatment in the last decade." (PMID 34952595, 2021). "T cell exhaustion is one of the hallmarks of cancer, and typical characteristics of exhausted T cells are as follows: increased inhibitory receptor expression, such as PD-1 and CTLA4, which leads to a low response to cancer cells." (PMID 34717645, 2021). "The combination of these molecules can potentially enhance the efficacy of CTLA-4 blockade in cancer immunotherapy." (PMID 34305910, 2021). "Therapeutics targeting immune checkpoint inhibitors (i.e., CTLA-4; PD-1, and PD-L1) have shown efficacy for subsets of cancer patients by unleashing an adaptive antitumor immune response." (PMID 33801967, 2021). "In advanced HCC and other cancer types, immunotherapeutic approaches have increasingly focused on monoclonal antibodies against CTLA-4 and PD-1 that block ICI pathways." (PMID 34071550, 2021). "Immunotherapy using monoclonal antibodies against PD1, PD-L1 or CTLA-4, has been demonstrated to be effective to treat various cancers." (PMID 33707569, 2021). "In the current state of cancer therapy, immune checkpoint inhibitors (ICIs), such as anti-PD-1, anti-PD-L1, and anti-CTLA4, have emerged as one of the most successful strategies in clinics and have used in the market to cure cancer." (PMID 35052713, 2021). "Cancer immunotherapy strategies, including PD-1/PD-L1 and CTLA-4 inhibitors, have become one of the most important therapy for melanoma." (PMID 34769455, 2021). "A number of studies have shown that overexpression of CTLA4 can block the T-cell cycle, thereby reducing the body’s specific immune function and leading to immune evasion of cancer cells." (PMID 34513829, 2021). "By blocking immune checkpoint proteins, including PD-1, PD-L1 and CTLA-4, with monoclonal antibodies, the immune system can overcome cancer’s ability to resist the immune responses and stimulate immune defenses against cancer." (PMID 33902630, 2021). "To date, multiple immune checkpoint inhibitors (blocking either CTLA-4, PD-1, or PD-L1) are approved for more than 15 different cancer entities, however, efficacy has so far been most promising in solid tumors." (PMID 33746972, 2021). "The development of numerous novel compounds or antibodies for combined therapy, which synergistically enhance the anti-cancer effects of anti-CTLA-4 or anti-PD-1 antibodies, is underway." (PMID 34702924, 2021). "Anti-cytotoxic T-lymphocyte antigen-4 (CTLA-4) and anti-programmed death-1 (PD-1)/PD-L1 therapies have achieved significant success in treating numerous cancers." (PMID 34234847, 2021). "Immune checkpoint inhibitors (ICIs) such as antibodies against PD-1, its ligand PD-L1, and CTLA-4 block these immune inhibitory molecules and restore the anti-tumor activity of cytotoxic T cells, resulting in eradication of cancer cells." (PMID 34369137, 2021). "Nevertheless, cancer immunotherapies such as CTLA-4 and PD-1 inhibitors are effective only in a minority of patients, therefore, there is still an urgent need for strategies to expand the population that can benefit from these novel therapies." (PMID 34158625, 2021). "The advent of immune checkpoint inhibitors (ICI) such as anti-cytotoxic T-lymphocyte-associated protein 4 (CTLA4), anti-programmed death protein-1(PD-1), and anti-PD-1 ligand 1 (PD-L1) has revolutionised cancer treatment in the last decade." (PMID 34359684, 2021). "Early clinical trials reported that anti-CTLA4 provided durable clinical responses and improved overall survival in a fraction of cancer patients." (PMID 35154081, 2021).
cancer (continued). "Recently, wide use of immune checkpoint inhibitors (ICIs), which mainly target CTLA-4 and the programmed death receptor/ligand 1 (PD-1/PD-L1) in cancer immunotherapies, improved durable responses in some advanced cancer patients." (PMID 35003126, 2021). "The most well-known checkpoints in the context of cancer immunotherapy are CTLA-4 and programmed cell death protein 1 (PD-1, CD279), which are transmembrane molecules expressed by T lymphocytes after their activation." (PMID 33540543, 2021). "Checkpoint inhibitors such as anti-PD-1 (programmed death 1), anti-PD-L1 (programmed death ligand 1), or anti-CTLA-4 (cytotoxic T lymphocyte antigen 4) antibodies are widely used in cancer immunotherapy." (PMID 34200219, 2021). "Antibody therapies called immune checkpoint inhibitors (ICIs) targeting molecules like CTLA-4, PD-1, and its ligand, PD-L1, are now commonly used in a wide variety of cancers and will be discussed in detail further on in this review." (PMID 34512641, 2021). "ICIs such as anti-CTLA-4 antibodies are used to block these signals and, hence, stimulate the elimination of cancer cells." (PMID 33078260, 2021). "Together, the data here support a role for sCTLA-4 in cancer immunoregulation, which is almost certain to influence current therapeutic approaches based on anti-CTLA-4 antibodies." (PMID 35069536, 2021). "NK cells have emerged as contributors to the effect of cytotoxic T lymphocyte-associated protein 4 (CTLA4), LAG3, and PD-1 in cancer patients, suggesting that immune checkpoint receptors regulate NK cell activity under pathological conditions." (PMID 34220833, 2021). "Since then, a total of seven types of ICIs targeting CTLA-4 and PD-1/PD-L1 have been approved for cancer immunotherapy in the last decade." (PMID 34439774, 2021). "TMB, TIL frequency, MMR deficiency and predicted neoantigen load all correlate with clinical responses to checkpoint blockade by both a-CTLA4 and a-PD-1 across a range of cancers." (PMID 34439399, 2021). "Recently, inhibiting immune checkpoints, such as cytotoxic T lymphocyte-associated protein 4 (CTLA4), programmed death 1 (PD1), and programmed death-ligand 1 (PD-L1), has shown clear benefits in the survival of cancer patients." (PMID 34248650, 2021). "Unfortunately, a certain percentage of patients with cancers still fail to respond to therapies that target CTLA-4 and PD-1/PD-L1." (PMID 34680601, 2021). "Data support similar mechanisms of action in cancer patients treated with the anti-fully human IgG1 anti-CTLA-4 mAb Ipilimumab." (PMID 34503073, 2021). "As a suppressor of the cancer-immunity cycle, lymph node regulatory T cells interact with CTLA-4 and co-stimulatory molecules such as CD80 and CD86 expressed on DCs to suppress T cell priming." (PMID 34071550, 2021). "Immune checkpoint CTLA-4 and PD-1 inhibitors revolutionized cancer research in the last decade and brought immunology back to the spotlight in therapeutic development." (PMID 34235155, 2021). "Currently, the most reliable sites for cancer treatment are the CTLA-4- and PD-1-activated immune T cells." (PMID 33955820, 2021). "Allison with his team initiated to approach this strategy at the end of 1994: they achieved therapeutic response in pre-clinical models of mouse cancers by treatment with the first immune checkpoint blockade agent (i.e. antibodies against CTLA-4)." (PMID 35201440, 2021). "For example, cancer immunotherapy by CTLA-4/PD-1 blockade was activated in ACT-S&HR-P patients (mean differences > 0, P < 0.05, Wilcoxon rank-sum test, the same below)." (PMID 34465315, 2021). "Recently, immune checkpoint inhibitors (ICIs) and monoclonal antibodies against immune checkpoint molecules, such as anti-CTLA-4, anti-PD-1 and anti-PD-L1, have been studied in various types of cancers, and these agents are routinely used in the clinic." (PMID 34881181, 2021).